SNORD114-15 (small nucleolar RNA, C/D box 114-15)
Synonyms: 14q(II-15)
Gene: Small nucleolar RNA gene on chromosome 14 (100,972,670 to 100,972,741, forward strand). Ensembl gene ENSG00000201557.
Gene Ontology:
Biological process: RNA processing
Cellular component: nucleolus
Homologues: Orthologues: chimpanzee SNORD114-15 (100% identical), macaque SNORD114-15 (96% identical). Paralogues in human: SNORD114-9 (93% identical), SNORD114-21 (92% identical), SNORD114-23 (92% identical), SNORD114-22 (90% identical), SNORD114-26 (90% identical), SNORD114-28 (89% identical), SNORD114-25 (88% identical), SNORD114-5 (88% identical), SNORD114-20 (86% identical), SNORD114-3 (86% identical), SNORD114-6 (86% identical), SNORD114-12 (83% identical), and 26 more.